IL1B (interleukin 1 beta)
Diseases named in the same sentence as IL1B in open-access papers (continued):
Sharing a sentence is not in itself a finding about the gene and the disease.
co-infection (continued). "The intensity of brown color revealed that TNF-α and IL-1β in murine mammary gland was upregulated in the co-infection group than the H. ovis and T. pyogenes individual infectiongroups in immunohistochemical analysis." (PMID 35224069, 2021). "In contrast, this co-infection in RAG2 females downregulated expression of several cytokines such as Il-1β, Il-17A, Ifnγ, Tnfα, and Il-13 only at 10 WPI, but increased transcription of colonic Il-22 at 21 WPI." (PMID 33255175, 2020). "In our severe model, IFN-γ and IL-1β were upregulated, while IL-10 was down-regulated during co-infection in IL-6−/− mice." (PMID 32038632, 2019). "pneumophila promoted an additive effect on IL-1β secretion, however, the co-infection of L.g.+ with flaA−L." (PMID 31754185, 2019). "LZD, vancomycin, or clindamycin significantly decreased pulmonary IL-6 and mKC levels at 4 h and the IFN-γ level at 24 h after MRSA co-infection, while the levels of IL-1β, TNF-α, and IL-12 were similar to those of the placebo group." (PMID 31849655, 2019). "Specifically, production of key proinflammatory cytokines (e.g., IL-1α and IL-1β), chemokines (e.g., CCL20 and CXCL8), and VEGFA was markedly downregulated during co-infection with either HCMV variant, reflecting the known synergistic interference between the two pathogens." (PMID 40980889, 2025). "Coinfection suppresses the type I interferon (IFN) response, activates the inflammasome and associated pathways, and concurrently triggers the massive secretion of pro-inflammatory cytokines (e.g., IL-6, TNF-α, IL-1β)." (PMID 41561948, 2025). "In piglets treated with the orally administered engineered strain, the levels of IL-1β, IL-6, and IL-10 in the co-infection group were lower than those in the challenge group, indicating that the inflammatory response caused by PEDV was milder in the co-infection group." (PMID 38430229, 2024). "We observed an increase in IL-1β in HBV/HDV co-infection vs. HBV mono-infection (p < 0.05)." (PMID 37877022, 2023). "Excluding co-infection with soil-transmitted helminths, individuals with C. sinensis still had significantly higher antigen-specific IgG and IgE levels, and diminished serum levels of IL-1β, IL-2, IL-4, IL-12p70, IL-17A, IFN-γ and TNF-α." (PMID 36083861, 2022). "Co-infection elevated the levels of both cytokines, especially IL-1β." (PMID 36389843, 2022). "In this study, we additionally report the regulation of proinflammatory (IL1-α, IL1-β, IL6, IL8, IL18, and TNF-α) and regulatory (IL10, IL22, IL23, and IL33) cytokines associated with single-PDCoV and -PEDV infection, as well as PDCoV/PEDV co-infection." (PMID 36376395, 2022). "At the protein level, it is also confirmed that co-infection has an additive effect on IL-1β." (PMID 34513970, 2021). "The top three markers contributing most to overall network density by AUC in the subgroup of those without HIV-1 co-infection were CXCL10, C-reactive protein, and IFNα2, whereas the top three markers in the subgroup of those with HIV-1 co-infection were IL-17A, IL-1β, and TNFα." (PMID 34386782, 2021). "While nitric oxide was shown to have an inhibitory effect on the NLRP3 inflammasome, we observed that high levels of nitric oxide and IL-1β coincided during co-induction with soluble uric acid and K. pneumoniae and the opposite was observed during uric acid and S. aureus co-infection." (PMID 33322651, 2020). "In regard to the immunity of individual patients, a previous study showed that co-infection has been associated with a strong activation of acute phase response, such as Interleukin 6 (IL-6), Tumor necrosis factor-α (TNF-α), and IL1-β and also Th1 cytokines (IFN-γ and IL-12)." (PMID 31522680, 2019). "To examine the immune profile of individuals with co-infection, we compared the concentration of 15 immune markers (IL-1β, IL-6, IL-8, TNF-α, IL-7, G-CSF, MCP-1/CCL2, MIP-1-α/CCL3, IL-12, IFN-γ, IL-13, IL-17A, GM-CSF, IL-10, and TGF-β1) among the three groups using Kruskal-Wallis ANOVA." (PMID 27128316, 2016).
co-infection (continued). "To test the efficacy of bead co-infections on rescuing immune suppression, we co-infected murine bone marrow derived macrophages (mBMDM) with wild-type F. tularensis bound to beads with either ΔpdpC or ΔripA and measured IL-1β secretion." (PMID 24505427, 2014). "Interestingly, during co-infection in mice deficient in IL-1 receptor type 1 (Il1r1−/− mice), the lack of IL-1β signaling is compensated for by TNF-α activation of recruited neutrophils." (PMID 36829255, 2023). "Comparable severity of cecal pathology between Hh+Hp and mono-Hh mice was in agreement with the finding that co-infection with Hp did not significantly enhance cecal transcription of key ILCs 1/3-associated genes including Ifnγ, Tnfα, Il-1β, and Il-17A at 21 WPI." (PMID 33255175, 2020). "In contrast, co-infection upregulated the induction of IFN-β, IFN-λ2/3, IL-1β, and TNF-α expression." (PMID 40431161, 2025). "In wild-type zebrafish, A. salmonicida infection repressed ifn3 but upregulated pro-inflammatory cytokines (il-8, il-1β, il-17, tnfα); GCRV-II infection induced ifn1, ifn3, il-8, and il-17; and co-infection upregulated ifn1, ifn3, il-8, and tnfα." (PMID 40920830, 2025). "Co-infection of PAMs with HP-PRRSV-2 strain NJGC and M. hyopneumonia increased IL-1β expression by more than 10 folds." (PMID 38547254, 2024). "Namely, we observed a significant decrease in the production of IFN-γ, TNF-α, IL-1β, IL-15, and IL-17 in patients with HIV/TB coinfection compared to the group of patients with HIV-1 and TB monoinfections." (PMID 37376629, 2023). "At the same time, a drastic decrease in the plasma levels of IFN-γ, TNF-α, Il-1β, IL-15, and IL-17 was detected in patients with HIV/TB coinfection compared to patients with HIV-1 or TB monoinfections." (PMID 37376629, 2023). "In summary, we have shown that patients with HIV-1/TB coinfection are characterized by reduced plasma levels of five proinflammatory cytokines: IFN-γ, TNF-α, Il-1β, IL-15, and IL-17, which are crucial for the control of both infections." (PMID 37376629, 2023). "Further, TNF-α, IL-1β, and IL-10 levels correlated with ALT suggesting a role in liver damage in the setting of co-infection." (PMID 37877022, 2023). "The increased levels of caspase-1 and IL-1β exhibited by ART-treated HIV-infected adults with HIV viral suppression (without coinfections) may contribute to noncommunicable diseases risk among ART-treated adults with chronic immune activation among adults aging with HIV." (PMID 37953818, 2023). "A previous study showed that co-infection of PAMs with PRRSV and Mycoplasma hyopneumoniae considerably increased the expression of pro-inflammatory cytokines TNF-α and IL-1β." (PMID 36992486, 2023). "Of note, although the GAS-induced overexpression of Il1b was also observed in the IAV+GAS group, co-infection entirely abrogated the secretion of mature IL-1β, which suggests that a preceding IAV infection compromised innate immune sensing of Streptococci." (PMID 36365071, 2022). "Co-infection tended to promote inflammation with heightened IFN-γ and IL-1β and diminished IL-10 levels when compared to monoinfections." (PMID 36389843, 2022). "Co-infection led to a predominant inflammatory milieu, with reduced IL-10 and TGF-β, and/or promotion of IFN-γ and IL-1β release." (PMID 36389843, 2022). "The IL-1β mRNA expression level increased gradually and peaked at 5 dpi with FAdV-4-HB1501 in both the FAdV-only and IBDV-FAdV co-infection groups." (PMID 33926543, 2021). "It is found that co-infection of PRRSV with HPS can increase the expression of pro-inflammatory cytokines such as TNF-α, IL-1β, and IL-8 in PAM cells." (PMID 34513970, 2021). "The co-infection with TVV+TV and P. bivia synergistically upregulated galectin-1, -9 and IL-1β (p <0.001)." (PMID 34422675, 2021). "TV-HPV co-infections HPV in contrast showed lower levels of galectin-9 (p <0.05), IL-1β and IL-8 (p <0.001)." (PMID 34422675, 2021).
co-infection (continued). "Compared with the group infected with GTPV alone, the expressions of IL-1β, IL-6, IL-10, and IFN-α in the co-infection groups were inhibited." (PMID 33827620, 2021). "In our study, the expression levels of inflammatory cytokines such as IFN-β, IL-1β, and TNF-α in the trachea, lungs, and kidneys were greater in the co-infection groups, especially in the IBV/H9N2 group, than in the single-infection IBV and H9N2 groups." (PMID 35211536, 2021). "In addition, the presence of more IL-17A-producing γδ and non-γδ T cells in early lesions (1–7 days), and L. major antigen-responsive Th17 cells after 28 days of coinfection, with a corresponding increase in IL-1β, may recruit more naïve neutrophils into the inflammatory site." (PMID 31107882, 2019). "The levels of TNF-α, IL-1β, IL-6, IL-10, IL-12, mKC, and IFN-γ were significantly increased at 4 h or/and 24 h after MRSA co-infection." (PMID 31849655, 2019). "In contrast, the HBV/HIV coinfection group has a different unique profile with GM-CSF-IL-4- IL-2-IFN-γ-IL12p70; and IL-7-IL-10 -IL1-β grouping together." (PMID 30815625, 2019). "We observed that HKSA induced robust IL-1β production from monocytes, and that exposure to HKSA with influenza virus co-infection increased the early IL-1β production of monocytes." (PMID 29997328, 2018). "The co-infection with H3N2 SwIV and either SW114 or Nagasaki induced higher levels of IL-1β, TNF-α, IL-6, IL-12 and IL-10 compared to mock or H3N2 SwIV infection alone." (PMID 23157617, 2012). "Notably, during co-infection, IL6 replaced IL-1B among the top five upregulated genes, suggesting a shift toward IL6-STAT3 mediated inflammation." (PMID 40771952, 2025). "Along these lines, our data from the co-infection experiments using S. aureus and H1N1 showed that in the presence of bacteria, at least some pro-inflammatory cytokines (i.e., IL-1β, IL-6, and TNF-α) and type II interferon IFN-γ are elevated on the protein level by H1N1 in M2-MDMs by tendency." (PMID 38261967, 2024). "Thus, OKF6/TERT2 cells were infected with P. gingivalis, F. nucleatum, the co-culture of both bacteria, and the co-infection of both bacteria and then the mRNA levels of TNF-α, IL-1β, IL-6, and IL-8 were determined using RT-qPCR." (PMID 38612423, 2024). "Additionally, some reports have described that the co-infection of both bacteria promotes increases in the expressions of TNF-α, IL-1β, and IL-6 in murine in vivo models." (PMID 38612423, 2024). "Additionally, co-infection of pigs with NADC30-like PRRSV-2 strain SDlz1601 and S. suis upregulated IL-1β, IL-6, IL-8, TNF-α, CCL4, IL-10, and INF-β in PAMs." (PMID 38547254, 2024). "Nevertheless, the differences in the production of IL-1β between the two groups with HIV/TB co-infection with and without TB recurrence were large enough to identify statistical differences between those groups." (PMID 38790916, 2024). "Furthermore, endonuclease therapies may prove safer than cytokine-blocking monotherapies, as they are unlikely to increase the risk of microbial co-infection associated with the neutralization of cytokines that are critical for immune defence such as IL-1β, IL-6 or GM-CSF." (PMID 39009040, 2024). "Additionally, pro-inflammatory cytokines IL-1β, IL-6, CXCL2, and TNF-α are downregulated during co-infection compared to P. aeruginosa single-infection." (PMID 37305417, 2023). "While the co-infection of A. actinomycetemcomitans with La5 resulted in reduced levels of all mediators, the co-infection with Lr32 promoted reduced levels of CXCL-8 and GM-CSF but increased the production of IL-1β." (PMID 35602018, 2022). "We showed that if IL-1β, TNFα and OSM were present in uninfected excisional skin lesions, IL-17A, IL-17F and IL-22 were specifically produced after S. aureus and P. aeruginosa co-infection of the lesions." (PMID 36275755, 2022).
co-infection (continued). "To examine whether co-infection alters the induction patterns of cytokines and chemokines, we measured the serum levels of IP-10, MCP-1, TNF-α, IL-1-β, IL-6, IL-10, and IFN-γ over the course of infection using ELISA." (PMID 34711897, 2021). "Galectin-9, IL-1β and chemokines were up in TV-HIV and down in TV-HPV co-infections." (PMID 34422675, 2021). "Expression of CCL2 remained elevated in lung of animals with co-infection while moderate, though non-significant, reductions of IL-1β and IL-6 were observed compared to the TB group." (PMID 32373548, 2020). "This increase depended on Syk activation, as R406-treated macrophages showed no increase in IL-1β levels upon co-infection with WT and Cgyps1–11Δ cells." (PMID 29491142, 2018). "In a mouse model of vulvovaginal candidiasis (VVC), the fungal burden and the levels of pro-inflammatory cytokines, IL-1β, IL-6 and TNF-α showed a increase on co-infection with S. agalactiae, while the level of TH17 T cells and IL-17 in the cervicovaginal lavage fluid were significantly decreased." (PMID 29527193, 2018). "In vitro TIM3 blockade—in co-culture experiments with MTB-infected macrophages from TB patients with or without HIV co-infection—promotes bacterial killing and enhances IL-1β secretion by infected cells, as well as the IFN-γ release by T cells." (PMID 28025511, 2016). "With the described co-infection method, neighboring wild-type bacteria functionally complement IL-1β suppression in ΔripA infected cells but not ΔripA intracellular proliferation." (PMID 24505427, 2014). "Besides, significantly decreased semen levels of IL-6 and IL-1β were detected in HR-HPV patients regardless of the presence of coinfections, while significantly reduced levels of IL-10 were only detected in HR-HPV+Coinf- patients." (PMID 39258253, 2024). "Elevated TGF-β production in PBMCs from patients with HIV/TB co-infection than from healthy controls was also observed, and high level of TGF-β in HIV patients might be a reason for defective MTB-specific IL-1β, IL-2 production and activation of latent TB in HIV." (PMID 37483385, 2023). "The increased expression of pro-IL-1β in monocytes/macrophages or other cells by H. pylori infection, make them vulnerable to NLRP3 inflammasome activation through increased concentration of ATP, MSU, ROS or environmental factors or co-infection with other inflammasome activating bacteria." (PMID 32230726, 2020). "The hypothalamus appeared to be particularly responsive to lung co-infection, as we did not observe any difference in microglial or astrocyte morphology in the hippocampus and whilst TNFα expression was increased, IL-6, IL-1β and CCL-2 expression were unaltered." (PMID 29980196, 2018). "Co-infection did not blunt expression of typical antibacterial cytokines (il1b and tnfa); however, both type I IFN and the anti-inflammatory cytokine il10 were induced by the viral infection prior to bacterial superinfection, suggesting a contribution to the observed phenotype." (PMID 29881380, 2018). "Thus the decrease of IL-1β secretion during co-infections was not due to fewer ΔripA infecting each cell." (PMID 24505427, 2014). "Finally,the mRNA levels of several cytokines were determined, and showed that the transcription of IFNB1, TNF, IL1B, and OASL was higher in the co-infection group than in the singly infected group, which may have been the consequence of increased PEDV replication." (PMID 37065133, 2023). "Interestingly, non-HIV patients with co-infection and pneumocystosis alone showed lower levels of SP-A, IL-1β, TNF-α, IFN-γ, IL-18, IL-17A, and IL-23 than histoplasmosis patients, suggesting an immunomodulatory ability of P. jirovecii over H. capsulatum response." (PMID 34829225, 2021).
co-infection (continued). "This increased expression of il1b in SINV + Shigella co-infections is mostly seen in late (24 h) but not early (6 h) time after Shigella injection, paralleling the increased bacterial burden of these animals, making it unclear whether it is a cause or a consequence of higher bacterial loads." (PMID 29881380, 2018). "Our findings suggest that the cytokines TNF-α, IL-1β, and IFN-γ are central to the immune response in HIV-CC co-infection whereas others like IL-18 are not." (PMID 40046043, 2025). "Other cytokines including TNFα, IL-1β and IFN-β were also induced by IAV and SP; however, no significant change in expression was found following co-infection." (PMID 23421931, 2013). "In addition, we assessed inflammatory gene expression in the hippocampus, and whilst TNFα was significantly increased in co-infected mice, IL-6, IL-1β and CCL-2 were not altered by single- or co-infection treatment." (PMID 29980196, 2018).